HLA-G (major histocompatibility complex, class I, G)
Diseases named in the same sentence as HLA-G in open-access papers (continued):
Sharing a sentence is not in itself a finding about the gene and the disease.
endometriosis (16 papers, 2017 to 2025). The growth of functional endometrial tissue in anatomic sites outside the uterine body. "Certain polymorphisms of HLA-G protected against endometriosis, and polymorphisms of LILRB1 and LILRB2 were associated with susceptibility to endometriosis and its progression." (PMID 35628346, 2022). "In endometriosis, genetic variants in HLA-G and LILRB1/2 are suggested to contribute to the development of the disease and its progression." (PMID 35877415, 2022). "In the present study we found that susceptibility to and the severity of endometriosis are associated with polymorphisms in the HLA-G, LILRB1 and LILRB2 genes." (PMID 29234882, 2018). "HLA-G may be associated with the development of endometriosis, as it is expressed in both the in situ and ectopic endometria of patients with endometriosis and expressed at abnormally high levels in peritoneal endometriotic lesions." (PMID 35720413, 2022). "HLA-G may act similar to IC molecules presented on cytotoxic T cells (CD8+T cells), they have found HLA-G accompanied sPD-L1 and sCTLA-4 may implicated in the pathological mechanisms of endometriosis-related infertility." (PMID 34777357, 2021). "Therefore, the aim of this retrospective study was to evaluate the association of the SNPs in genes coding for KIR2DL4, LILRB1 and LILRB2 receptors and their ligand HLA-G with susceptibility to and severity of endometriosis as potential non-invasive markers for the diagnosis of this disease." (PMID 29234882, 2018). "The analysis of polymorphisms of HLAG gene coding for a ligand for KIR2DL4 and LILRB2 receptors has revealed that endometriosis in Polish women is associated with a lower frequency of its −964GG genotype (−964A > G; rs1632947)." (PMID 31540116, 2019). "The data on HLA-G expression in endometrial tissue from healthy individuals and patients with endometriosis are controversial." (PMID 29234882, 2018). "Soluble HLA-G (sHLA-G) was found in the peritoneal fluid in similar concentrations in control subjects and in mild and severe endometriosis." (PMID 29234882, 2018). "However, the eutopic endometrium in endometriosis shows reduced HLA-G expression, potentially impairing endometrial receptivity and decidualization and contributing to implantation failure and miscarriages." (PMID 40003650, 2025). "Although several studies compared endometriosis with HLA-G and HLA-C,24, 25, 26 and some studies compared endometriosis to anti-tissue transglutaminase IgA,18, 19 there have been no reports so far investigating the relation between endometriosis and HLA-DQ2 and HLA-DQ8." (PMID 38432123, 2024). "The increased inhibition of NK cell activity at the peritoneal level in endometriosis was also explored through NK cell inhibitory ligands in three studies, which analyzed HLA-G expression in peritoneal fluid using different methods (ELISA, Western blotting, and immunohistochemistry)." (PMID 36613776, 2022). "The study of Polish scientists analyzed whether polymorphisms of HLA-G, KIR2DL4, LILRB1 and LILRB2 genes may affect susceptibility to endometriosis and disease progression." (PMID 34638893, 2021). "Endometriosis is also associated with allelic variants of HLAG, thus suggesting that the LILRB1/HLA-G interaction may play a part in the inhibition of NK cell activity and the development of the disease." (PMID 31540116, 2019). "In this study we investigated whether HLA-G, KIR2DL4, LILRB1 and LILRB2 polymorphisms may influence susceptibility to endometriosis and disease progression." (PMID 29234882, 2018). "The putative role of HLA-G in the etiopathogenesis of endometriosis may be strengthened by our further observation that the disease is also associated with polymorphism in LILRB1 and LILRB2 genes coding for HLA-G receptors." (PMID 29234882, 2018). "Furthermore, the absence of HLA-G expression in peritoneal fluid highlights that immune dysfunction associated with endometriosis derives from both NK inhibitor receptor and ligand overexpression." (PMID 36613776, 2022).
endometriosis (continued). "GPER/miR-148a/HLA-G signaling could mediate cell apoptosis in endometriosis." (PMID 32850438, 2020). "No other reports on the role of HLA-G polymorphisms in endometriosis have been published so far." (PMID 29234882, 2018). "All the studies reached the same result: there were no significant statistical differences in HLA-G in the peritoneal fluid of endometriosis subjects compared with the controls." (PMID 36613776, 2022). "The most important conclusion was that HLA-G and the receptors LILRB1 and LILRB2 may play a crucial role in eliminating endometriotic cells and the development of endometriosis." (PMID 35628346, 2022). "Endometriosis pathogenesis seems to be marked by the overexpression of NK inhibitor receptors (KIRS), namely, CD158a+, KIR2DL1, CD94/NKG2A, PD-1, NKB1, and EB6, and inhibiting ligands such as PD-L1, HLA-E, HLA-G, and HLA-I." (PMID 36613776, 2022). "A retrospective study showed that polymorphisms in HLA-G, LILRB1, and LILRB2 genes contributed to the susceptibility and severity of endometriosis, but not KIR2DL4 polymorphisms." (PMID 35720413, 2022). "With this technique, they found that the glandular epithelia of 13 out of 14 peritoneal lesions (92.8%) contained the HLA-G gene transcript, but this was not present in the eutopic endometrium (control and endometriosis samples)." (PMID 36613776, 2022). "It should be stressed, however, that the functional role of HLA-G in the context of KIR2DL4 and LILRB1 receptors in course of endometriosis remains unknown and requires further investigations." (PMID 31540116, 2019). "However,it is worth to mention that other class of MHC genes located near HLA-G (HLA-DQ and HLA-DRB1) have already been published in the context of endometriosis." (PMID 29234882, 2018). "As per their results, endometriosis pathogenesis is marked by the overexpression of NK inhibitor receptors (KIRS), namely, CD158a+, KIR2DL1, CD94/NKG2A, PD-1, NKB1, and EB6, and inhibiting ligands such as PD-L1, HLA-E, HLA-G, and HLA-I in ectopic endometrial lesions." (PMID 36613776, 2022). "However, there are studies that have shown that the serum levels of IL-10, TNF-alpha, and soluble HLA-G (sHLA-G) alone are not sufficient for differentiating between endometriosis and cancer, despite being significantly increased compared to their levels in benign lesions." (PMID 38337827, 2024).
multiple myeloma (16 papers, 2014 to 2026). "Accumulating evidence indicates that elevated HLA-G expression contributes to tumor immune evasion and influences clinical outcomes in patients with leukemia, lymphoma, and multiple myeloma." (PMID 42083155, 2026). "In human multiple myeloma, the regulatory potency of HLA-G-acquired effector T cells is similar to that of natural regulatory T cells (nTregs)." (PMID 39741180, 2025). "Co-culture of endothelial HUVEC and myeloma cells stimulated formation of new tubes from endothelial cells, when the cultured medium was supplemented with IL-6 or was depleted of HLA-G." (PMID 38877399, 2024). "The ubiquitinated HIF-1α and HLA-G proteins were identified in the three myeloma cell lines after 4-h treatment with IL-6." (PMID 38877399, 2024). "When stimulated with IL-6, HIF-1α and HLA-G in the myeloma cell lines were subjected to ubiquitination and degradation." (PMID 38877399, 2024). "To explore it mechanistically, we established a HIF-1α-knockout (KO) cell line established by CRISPR/Cas9, and found that HLA-G expression in human myeloma cell lines under hypoxia was governed by HIF-1α." (PMID 38877399, 2024). "In myeloma patients, HLA-G transfer from tumor plasma cells to T cells via trogocytosis was associated with a poor clinical outcome." (PMID 36311782, 2022). "In clinical settings, CD25–FoxP3– T cells can acquire HLA-G from HLA-G+ malignant plasma cells in multiple myeloma patients." (PMID 30319626, 2018). "In multiple myeloma and B-cell leukemia, interaction with HLA-G and ILT2 inhibitory receptor induces tumor cell apoptosis." (PMID 29285306, 2017). "We thus explored whether co-immunoprecipitation of PARKIN with HIF-1α and HLA-G from myeloma cells could be expedited by IL-6." (PMID 38877399, 2024). "The evidence that HLA-G may inhibit tumor cell proliferation was consolidated by studies using bone marrow (BM) samples from multiple myeloma patients where HLA-G limits CD138− stem cell differentiation into CD138+ multiple myeloma cells." (PMID 35328349, 2022). "HLA-G expression could be detected in immune privileged organs and many tumor entities such as leukemia, multiple myeloma, and non-Hodgkin and Hodgkin’s lymphoma." (PMID 29602958, 2018). "Indeed, HLA-G inhibits the proliferation of human B cell lymphomas, myelomas, and B cell leukemia expressing at their surface the receptor ILT2." (PMID 24800261, 2014). "Aberrant HLA-G expression was also described in other hematological malignancies such as non-Hodgkin lymphoma, chronic lymphatic leukemia, and multiple myeloma as well as in solid tumors, such as breast cancer, and non-small cell lung cancer, particularly in advanced disease stages." (PMID 29602958, 2018). "We thus developed two mouse models of myeloma xenografts in intra-bone marrow (BM) and underneath the skin, and found a strong correlation between HLA-G and HIF-1α expressions in hypoxic BM, but not in oxygenated tissues." (PMID 38877399, 2024). "In hematological malignancies, especially in B cell tumors such as multiple myeloma, non-Hodgkin B-lymphoma, and B-CLL, HLA-G may exert anti-tumor activities through the direct inhibition of tumor cell proliferation." (PMID 35328349, 2022). "For instance, it is known that some but not all B leukemia cells and multiple myeloma cells from the same tumor can express HLA-G, which is capable of protecting them from NK cell cytolysis, and thus constitutes an immune escape mechanism." (PMID 25887663, 2015).
renal carcinoma (16 papers, 2012 to 2025). A carcinoma arising from the epithelium of the renal parenchyma or the renal pelvis. "The overexpression of miR-148a-3p downregulates HLA-G expression and induces cell death in renal cancer cells, activating NK cell cytotoxicity." (PMID 39759512, 2024). "Conversely, the high expression of miR-148a and miR-152 has been demonstrated to be related to the reduced HLA-G protein level in renal cancer and colon cancer." (PMID 38310272, 2024). "Classical human leukocyte antigen G (HLA-G) is commonly expressed in renal cancer cells, inhibiting the cytotoxic activity of T and NK cells." (PMID 39759512, 2024). "Expressions of markers such as CD40, α5 integrin, CD80, CD86, and HLA-DR are downregulated in monocyte-derived DCs after co-incubation with renal cancer derived-EVs carrying HLA-G, which can be inhibited by anti-HLA-G-antibody." (PMID 36405712, 2022). "HLA-G bearing EV derived from renal cancer stem-cells were shown to induce the inhibition of dendritic cell differentiation, thereby modifying immune responses towards tumor cells." (PMID 31382533, 2019). "In that study, HLA-G expression in renal cancer lesions (RCC) was evaluated by immunohistochemistry (IHC) with different HLA-G antibodies including mAbs 4H84 and 5A6G7." (PMID 30234020, 2018). "This possibility of immunotherapy targeting Qa-2 is shared by HLA-G, as HLA-G-derived peptides were able to induce a CTL response against HLA-G-expressing human renal carcinoma cells." (PMID 30574154, 2018). "In conclusion, the results of the present study indicate that renal cancer cells and in particular CSCs and derived EVs impair maturation of DCs and T cell immune response by a mechanism involving HLA-G." (PMID 26704308, 2015). "In renal cancer cells, HLA-G expression via partial de-methylation of its promoter was counted among the strategies used by malignant cells to escape immune response." (PMID 23265140, 2012). "To date, the origin of exosomal HLA-G remains inconclusive, but a previous study suggested it might be derived from stem cell-like cancer cells in renal cancer." (PMID 38310272, 2024). "Notably, unidentified HLA-G isoforms without an α1 domain were predicted based on RNA sequencing (RNA-seq), and several previously undescribed HLA-G isoforms have been identified in renal cancer samples." (PMID 32670296, 2020). "The recent discovery in renal carcinoma cells of new HLA-G transcripts, characterized by previously not described intron retention or exon skipping events, which cannot be recognized by the available antibodies increases the complexity in the field." (PMID 32733439, 2020). "By ELISA assay, the soluble HLA-G (sHLA-G) was barely detectable in cell free supernatants of renal cancer cells (not shown) and of fully differentiated DCs." (PMID 26704308, 2015). "Indeed HLA-G expression is widely documented in renal cancer cells, while no expression has been reported in normal renal cells." (PMID 23265140, 2012).
rheumatoid arthritis (16 papers, 2010 to 2025). A chronic, systemic autoimmune disorder characterized by inflammation in the synovial membranes and articular surfaces. "There are controversial reports concerning the impact of HLA-G gene polymorphism on rheumatoid arthritis (RA)." (PMID 27610404, 2016). "This study aimed at a systematic evaluation of soluble HLA-G (sHLA-G) in plasma of rheumatoid arthritis (RA) patients with long-lasting chronic inflammation." (PMID 25853899, 2015). "The HLA-G molecule is also one of the factors that contribute to the development of Rheumatoid Arthritis (RA), which involves chronic inflammation of the synovial membrane." (PMID 35154112, 2022). "Some drugs may also induce HLA-G production, such as methotrexate (MTX), one of the most used antirheumatic drugs for the treatment of rheumatoid arthritis (RA)." (PMID 24741620, 2014).
Infertility (14 papers, 2014 to 2025). "At the genotype level, HLA-G*01:01:02/01:04:01 was associated with an increased infertility and the recorded treatments, with respective OR = 5.06 (95%CI 1.22–21.02, P = 0.03) and OR = 9.07 (95% CI 1.22–39.50, P = 0.03)." (PMID 33947339, 2021). "HLA-G UTR4 was associated with a shorter time-to-pregnancy in couples undergoing infertility treatment and was found more frequent in healthy individuals than in asthmatic patients." (PMID 33859649, 2021). "In another study, HLA-G gene alleles *0106, *010106, *01010106 and *0105 N were significantly higher in patients with embryonic implantation failure on infertility treatments." (PMID 33947339, 2021). "The present study emphasized the association of lifestyle habit with the ICAM1 and HLA-G genes expression alteration and oocyte quality as an opinion for the deeper understanding of the etiology of infertile women with POR patients." (PMID 33953208, 2021). "Our study confirms a role of HLA-G polymorphism in infertility and soluble HLA-G in the early stages of pregnancy." (PMID 31993049, 2019). "It seems that by genotyping of HLA-G polymorphism, we can predict risk of implantation failure in infertile women after use of ART." (PMID 25469137, 2014). "For instance, the soluble HLA-G phenotype may be a useful diagnostic with clinical therapeutic utility for women with infertility or pregnancy complications." (PMID 34777357, 2021). "We can conclude that HLA-G polymorphism is associated with infertility." (PMID 31993049, 2019). "In this study, we evaluated the expression profile for ICAM-1 and HLA-G genes in the cumulus cells of infertile women with poor response to ovarian stimulation (POR) based on their healthy lifestyle habit." (PMID 33953208, 2021). "The aim of this research was to determine the levels of human leukocyte antigen G (HLA-G) and endometrial Natural Killer ((e)NK) cell percentages in uterine flushing samples from primary and secondary infertile women." (PMID 25764161, 2015). "HLA-G, IP-10, IL-1Ra, and IL-10 play critical roles in maintaining normal pregnancy, and their dysregulated expression is a significant factor contributing to infertility." (PMID 40375897, 2025). "Moreover, the HLA-G UTR-4 haplotype (possessing -964G, -725G, 14 bp del) was associated with a shorter time to achieving pregnancy in an infertility treatment setting when both female and male partners were carriers." (PMID 35111159, 2021). "We have deduced from our research that searching for single loci in HLA-G gene as a risk marker for infertility did not give the results expected." (PMID 31993049, 2019). "In this study, we investigated whether selected HLA-G polymorphisms and their protein levels measured in the plasma of patients undergoing IVF-ET could predispose an individual to infertility and RIF and influence pregnancy outcome." (PMID 31993049, 2019). "Our findings revealed that a major contributor to oocyte maturity disorder and infertility in the POR patients without a healthy lifestyle habit can be a reduction in ICAM1 and HLA-G transcript and proteins expression as well as hypermethylation of DNA in ICAM1 and HLA-G." (PMID 33953208, 2021).
leukemia (14 papers, 2010 to 2026). A malignant (clonal) hematologic disorder, involving hematopoietic stem cells and characterized by the presence of primitive or atypical myeloid or lymphoid cells in the bone marrow and the blood. "In this study, we explored the association of genetic variants at the 3’-untranslated region (3’-UTR) and 5’-upstream regulatory region (5’-URR) of HLA-G gene with the adverse outcomes of patients with leukemia receiving HSCT." (PMID 36911734, 2023). "Our study added new information on the regulation of HLA-G levels in leukemia." (PMID 35774498, 2022). "NKL cells are a leukemia cell line, thereby proteins as midkine might be strongly expressed and potentially bound as peptides to HLA-G." (PMID 32575403, 2020). "Moreover, they opem new clinical perspectives: HLA-G expression can be used as prognostic tumor biomarker to monitor disease state or as therapeutic target for improving immune responses against leukemia." (PMID 24741612, 2014). "The association of HLA-G polymorphisms with malignancies has been studied in a wide range of solid tumors, including breast and cervical cancers, but, thus far, it has not been evaluated in leukemia." (PMID 24741612, 2014). "Furthermore, the cytotoxicity assay showed that dNK-RPL exhibited significantly higher cytotoxicity against JEG3 (a human trophoblast cell line with HLA-G expression) and K562 leukemia cells compared to dNK-NOR." (PMID 38966071, 2024). "Human leukocyte antigen G (HLA-G) is an immune checkpoint protein (ICP) that is neoexpressed in most tumor cells as a way to evade immune attack and has been recently demonstrated as a useful target for chimeric antigen receptor (CAR)-T therapy of leukemia by in vitro studies." (PMID 34663641, 2021). "In addition, agonistic antibodies and human leukocyte antigen (HLA)-G, a natural ligand for KIR2DL4, induce the secretion of leukemia inhibitory factor and serine proteases from human mast cells, which have been implicated in pregnancy establishment and cancer metastasis." (PMID 32023940, 2020). "Analysis performed on blasts from patients with different leukemia, including Acute Myeloid Leukemia (AML), Acute Lymphoid Leukemia (ALL), and Chronic Myeloid Leukemia (CML), demonstrated that neither mRNA for any HLA-G isoforms nor HLA-G antigen was detected." (PMID 24741612, 2014).